ATXN3 (ataxin 3)
Diseases named in the same sentence as ATXN3 in open-access papers (continued):
Sharing a sentence is not in itself a finding about the gene and the disease.
colon cancer (4 papers, 2020 to 2024). "In alignment with our findings, it has been demonstrated that the oncogenic microRNA miR-25, frequently elevated in various human cancers, targets ATXN3 and suppresses its protein expression, thereby promoting colon cancer progression." (PMID 38815863, 2024). "As expected, the stable expression of Galectin-9 completely neutralized the increased tumor growth induced by ATXN3 suppression, indicating that ATXN3 impedes colon cancer cell growth by stabilizing Galectin-9." (PMID 38815863, 2024). "Collectively, these results affirm that ATXN3 functions as a tumor suppressor by enhancing Galectin-9-induced colon cancer cell death." (PMID 38815863, 2024). "Our study establishes ATXN3 as the inaugural Galectin-9-specific deubiquitinase and brings to light a tumor-suppressive role of ATXN3 in human colon cancer." (PMID 38815863, 2024). "As anticipated, ATXN3 ablation led to a pronounced increase in HCT116 xenograft colon cancer growth in RAG1 mutant mice." (PMID 38815863, 2024). "To investigate the potential role of ATXN3 in governing the tumoral expression of immune modulatory molecules, we created ATXN3 knockout colon cancer cells, including HCT116, CT26, and MC38." (PMID 38815863, 2024). "Future studies using both immune functional and immunocompromised (this study) mice to dissect the tumor intrinsic and extrinsic contributions of ATXN3 in colon cancer pathogenesis are needed." (PMID 38815863, 2024). "Intriguingly, ATXN3 acts as an endogenous deubiquitinase of Galectin-9, thereby targeting ATXN3 deletion resulting in the reduced Galectin-9 expression and apoptosis of colon cancer cells." (PMID 38815863, 2024). "Consistently, the loss of ATXN3 functions significantly enhanced the colony formation of HCT116 and MC38 colon cancer cells, which was entirely reversed by the expression of Galectin-9." (PMID 38815863, 2024). "Immunohistochemical staining revealed variable protein expression levels for both ATXN3 and Galectin-9 in colon cancers." (PMID 38815863, 2024). "Given that ATXN3 modulates tumoral PD-L1 expression to evade antitumor immunosurveillance, we opted to utilize a xenograft colon cancer model to examine the impact of ATXN3 on cancer growth in immune-compromised mice." (PMID 38815863, 2024). "Contrary to our expectations, targeted ablation of the ATXN3 gene resulted in a striking increase in colon cancer growth." (PMID 38815863, 2024). "Surprisingly, our findings demonstrate that ATXN3 exerts an antitumor effect in human colon cancers through potentiating Galectin-9-induced apoptosis." (PMID 38815863, 2024). "CRISPR-mediated ATXN3 deletion unexpectedly intensified colon cancer growth both in vitro and in xenograft colon cancers." (PMID 38815863, 2024). "Nevertheless, the treatment of ATXN3 knockout colon cancer cells with the proteasomal inhibitor MG132 completely restored Galectin-9 protein expression." (PMID 38815863, 2024). "Flow cytometry analysis confirmed similar levels of Galectin-9 expression in the stably expressed ATXN3 WT and KO colon cancer cells." (PMID 38815863, 2024). "Our study identifies the first Galectin-9-specific deubiquitinase and unveils a tumor-suppressive role of ATXN3 in human colon cancer." (PMID 38815863, 2024). "In contrast, only a modest but statistically significant reduction in PD-L1 expression was detected in human colon cancer HCT116 cells by ATXN3-targeted knockdown." (PMID 38038129, 2023). "As for colon cancer, it has been reported that miR-25 promotes cell growth, cell migration, and inhibits apoptosis via Ataxin-3 expression." (PMID 32982735, 2020). "Furthermore, immunohistochemistry staining revealed a significant reduction in both ATXN3 and Galectin-9 protein expression, along with a positive correlation between them in human colon cancer." (PMID 38815863, 2024).
colon cancer (continued). "Consequently, targeted ATXN3 ablation resulted in reduced Galectin-9 protein expression, thereby diminishing Galectin-9-induced colon cancer apoptosis and cell growth arrest." (PMID 38815863, 2024). "Therefore, a strong positive correlation between ATXN3 and Galectin-9 protein in human colon cancer tissues was detected." (PMID 38815863, 2024). "Additionally, flow cytometry analysis revealed a significant reduction in colon cancer cell death upon ATXN3 ablation, with Galectin-9 expression reversing the apoptosis of ATXN3-null colon cancer cells." (PMID 38815863, 2024). "The ectopic expression of Galectin-9 fully reversed the growth of ATXN3-null colon cancer in mice." (PMID 38815863, 2024). "Indeed, the targeted deletion of ATXN3 in human colon cancer cells, leading to a substantial reduction in Galectin-9, markedly intensified both HCT116 and MC38 colon cancer cell proliferation." (PMID 38815863, 2024). "Our study unveils a previously unknown tumor-suppressive function of ATXN3 in the progression of colon cancer." (PMID 38815863, 2024). "Contrary to current studies highlighting the tumor-promoting effects of ATXN3, our research uncovers a tumor-suppressive role for ATXN3 in colon cancers, suggesting that ATXN3 functions as a complex regulator in tumorigenesis, possibly exhibiting cancer-type-specific behaviors." (PMID 38815863, 2024). "Subsequently, we analyzed ATXN3 and Galectin-9 expression levels in human colon cancers." (PMID 38815863, 2024). "However, the role of ATXN3 in the development and progression of colon cancer remains largely unexplored." (PMID 38815863, 2024). "Subsequently, we established stable expression of Galectin-9 in ATXN3 wild-type and KO colon cancer cells to investigate whether reintroducing Galectin-9 expression could mitigate the heightened tumor progression observed upon ATXN3-targeted suppression." (PMID 38815863, 2024). "Subsequently, we investigated whether genetic suppression of ATXN3 enhances colon cancer progression in mice." (PMID 38815863, 2024). "Both ATXN3 and Galectin-9 protein expression levels exhibited a similar decrease in benign colon adenoma compared to colon adenocarcinoma, suggesting an early-stage involvement of ATXN3 and Galectin-9 reduction in colon cancer tumorigenesis." (PMID 38815863, 2024). "The miR-25/Ataxin-3 axis provides a novel insight into the pathogenesis of human colon cancer, particularly with respect to promote proliferation and metastasis of colon cancer, and Ataxin-3 represents a potential therapeutic target for human colon cancer." (PMID 32982735, 2020). "Furthermore, Galectin-9 has been recognized as a crucial positive regulator of mucosal immunity in combatting gut inflammation caused by the microbiome through the Th17-IgA axis, establishing an additional connection for ATXN3 in suppressing inflammation-induced colon cancer." (PMID 38815863, 2024). "Consistently, ATXN3 protein was identified through Western blotting in anti-Galectin-9 immunoprecipitants but not in normal rabbit IgG controls from HCT116 colon cancer cells." (PMID 38815863, 2024). "Conversely, the absence of ATXN3 expedited the degradation of Galectin-9 in colon cancer cells." (PMID 38815863, 2024).
narcolepsy (4 papers, 2013 to 2024). A sleep disorder characterized by a tendency for excessive sleepiness during the day which occurs even after adequate sleep in the nighttime. "In a murine model of narcolepsy, the orexin/ataxin-3 transgenic mouse, almorexant exacerbated spontaneous cataplexy, and possibly elicited cataplexy-like events in some wild type mice after wheel running activity." (PMID 24592208, 2014). "Th-gfp;orexin/ataxin-3 double transgenic (Th-gfp;orexin/ataxin-3) mice were used as a narcolepsy model." (PMID 23922890, 2013). "Experiments on the HCRT/ataxin-3 narcolepsy mouse model demonstrated that intracerebroventricular (ICV) injections of HCRT-1 can compensate for HCRT cell loss and reverse most of the narcolepsy symptoms including cataplexy." (PMID 24736646, 2014). "Orexin knockout mice and orexin/ataxin-3 mice also showed fragmentation of NREM sleep, which is consistent with the nocturnal awakenings often seen human narcolepsy." (PMID 23922890, 2013).
oral squamous cell carcinoma (4 papers, 2021 to 2024). "For example, for oral squamous cell carcinoma, it had been studied that down-regulated miR-619-5p promoted the proliferation, migration, and invasion abilities by enhancing ATXN3 expression in OSCC cisplatin-resistant cells." (PMID 36159990, 2022).
progressive ataxia (4 papers, 2015 to 2023). "SCA3-YAC-84Q mice expressing the human ATXN3 gene with 84 CAG repeats exhibit SCA3 related symptoms such as motor dysfunction, progressive ataxia, and presence of ATXN3 aggregates in neurons." (PMID 30086154, 2018).
Cataplexy (3 papers, 2012 to 2024). A sudden and transient episode of bilateral loss of muscle tone, often triggered by emotions. "In orexin/ataxin-3 narcolepsy mice, danavorexton reduced sleep/wakefulness fragmentation and cataplexy-like episodes during the active phase." (PMID 35994639, 2022). "In this regard, almorexant-treated rats appear somewhat similar to orexin null mutant or orexin/ataxin-3 mice which have disrupted sleep architecture (although these strains also exhibit cataplexy)." (PMID 22768296, 2012). "Thus, TAK-861 can ameliorate not only wakefulness fragmentation but also cataplexy-like episodes in orexin/ataxin-3 mice." (PMID 39242684, 2024).
gastric cancer (3 papers, 2015 to 2023). A primary or metastatic malignant neoplasm involving the stomach. "The expression of ATXN3 protein was decreased in the gastric cancer compared to noncancerous gastric tissue, and associated with tumor size, histologic differentiation, and Lauren classification." (PMID 37349820, 2023). "Importantly, further research on Ataxin-3 may offer a more comprehensive understanding of Ataxin-3 and might uncover the potential biomarkers for the progression of gastric cancer." (PMID 32982735, 2020). "Therefore, Ataxin-3 may serve as a potential intervention target for gastric cancer treatment." (PMID 32982735, 2020).
Obesity (3 papers, 2008 to 2026). Accumulation of substantial excess body fat. "Obesity was more prominent in females in both preprohypocretin knockout mice and orexin/ataxin-3 transgenic narcoleptic mice and was associated with higher serum leptin levels, suggesting a partial leptin resistance." (PMID 18706091, 2008).
prostate carcinoma (3 papers, 2023 to 2026). A carcinoma that arises from epithelial cells of the prostate gland. "Ataxin-3 removes K48-linked chains from YAP, stabilising YAP and thus promoting prostate cancer progression." (PMID 38497605, 2024). "As Hippo signaling is important for maintaining the stemness of tumor cells, we then examined the role of ATXN3 in prostate cancer stemness characteristics." (PMID 37349820, 2023). "Briefly, we transfected four nonoverlapping siRNA mixtures specific for each of the DUBs into prostate cancer cells and found that silencing ATXN3 significantly decreased YAP protein level in LnCap cells." (PMID 37349820, 2023). "It was found that ATXN3 depletion significantly reduced the oncosphere formation of prostate cancer cells." (PMID 37349820, 2023). "In the present study, we screened a DUB siRNA library and identified that a deubiquitinating enzyme, ATXN3, regulates prostate cancer cells proliferation, invasion, and stemness via the Hippo pathway." (PMID 37349820, 2023). "ATXN3 depletion significantly inhibited the G1/S phase transition and the colony formation ability of prostate cancer cells." (PMID 37349820, 2023). "The proliferation rate of prostate cancer cells treated with ATXN3 siRNAs was significantly suppressed compared with that in control cells." (PMID 37349820, 2023). "Besides, we observed a positive association between ATXN3 and YAP protein levels in human prostate cancer samples." (PMID 37349820, 2023). "Our results suggested that ATXN3 promotes prostate cancer progression by regulating YAP." (PMID 37349820, 2023). "We identified ATXN3 as a deubiquitinating enzyme that stabilizes YAP in prostate cancer." (PMID 37349820, 2023). "We then investigated whether ATXN3 co-localizes with YAP in prostate cancer cells, immunofluorescent staining demonstrated that ATXN3 and YAP co-localized in both the cytosol and nucleus of LnCap and C4-2B cells." (PMID 37349820, 2023). "Our study reveals a new regulation mechanism of YAP and indicating that ATXN3 might be further developed into a potential therapeutic target in prostate cancer." (PMID 37349820, 2023). "Furthermore, ATXN3 is overexpressed prostate cancer samples, suggesting that ATXN3 may play a role in the pathogenesis of prostate cancer." (PMID 37349820, 2023). "Finally, ATXN3 could promote tumor proliferation, invasion and stem-like properties of prostate cancer through YAP." (PMID 37349820, 2023). "In conclusion, our present study demonstrated that ATXN3 functions as a DUB responsible for YAP that promotes tumor growth, invasion, tumor stem-like properties of prostate cancer through stabilizing YAP protein." (PMID 37349820, 2023). "Since ATXN3 deubiquitinates and stabilizes YAP in prostate cancer cells, we then tested whether ATXN3 regulates these functions via modulating YAP." (PMID 37349820, 2023). "IHC analysis indicated that ATXN3 and YAP were both upregulated in prostate cancer samples." (PMID 37349820, 2023).
retinal degeneration (3 papers, 2019 to 2025). Degeneration of the retina. "For SCA3, Drosophila models expressing the C-terminal fragment of human ATXN3 with 78 or 82 CAG repeats led to retinal degeneration, abnormal eye morphology, and neuronal death." (PMID 41002431, 2025).
schizophrenia (3 papers, 2020 to 2022). A major psychotic disorder characterized by abnormalities in the perception or expression of reality. "When applying the constraint threshold, a single top-associated gene that failed the 10% BH-FDR threshold (ATXN3) appeared to have a somewhat similar p-value for schizophrenia." (PMID 33110418, 2020). "Importantly, the concentration range in which aripiprazole enhanced mutant ATXN3-mediated motor phenotype is potentially relevant in the clinical context, as previous imaging studies found analogous concentrations of this compound in the brain of schizophrenia patients." (PMID 35203579, 2022).
bladder cancer (2 papers, 2023 to 2024). "VCP also stabilized Beclin 1 and promoted autophagy in bladder cancer cells by downregulating ataxin-3." (PMID 37269429, 2023). "However, the role of ataxin-3 in bladder cancer remains unclear." (PMID 37269429, 2023).
cervical cancer (2 papers, 2025 to 2026). A primary or metastatic malignant neoplasm involving the cervix. "Although HIF-1α is known to influence deubiquitinases, its role in regulating ATXN3 in cervical cancer was previously unclear." (PMID 41507147, 2026). "Our study establishes ATXN3 as a context-dependent molecular switch in cervical cancer, showing opposing functions across subtypes: it is upregulated in HPV16+ SCC but downregulated in HPV18+ AC." (PMID 41507147, 2026). "Our study reveals a subtype-specific role for ATXN3 in regulating STAT5 signaling in cervical cancer." (PMID 41507147, 2026). "These consistent, opposing expression profiles suggest distinct subtype-specific roles for ATXN3 in cervical cancer development." (PMID 41507147, 2026). "These subtype-specific pathways provide a molecular rationale for ATXN3’s opposing functional roles across cervical cancer subtypes." (PMID 41507147, 2026). "This work thus provides a foundational framework for developing precision therapeutic strategies tailored to individual cervical cancer subtypes based on their distinct ATXN3 regulatory networks." (PMID 41507147, 2026). "Collectively, these results demonstrate that ATXN3 exerts opposing, context-dependent roles across cervical cancer subtypes, suppressing malignant phenotypes in C33A and HeLa while promoting them in SiHa cells." (PMID 41507147, 2026). "This study examines hypoxia’s role in regulating ATXN3 (ATXN3) across cervical cancer subtypes and its impact on tumor progression." (PMID 41507147, 2026). "Our study reveals that ATXN3 exhibits dual, context-dependent roles in cervical cancer—acting as either a tumor suppressor or an oncoprotein depending on histological and HPV status." (PMID 41507147, 2026). "To investigate the functional role of ATXN3 in cervical cancer, we successfully overexpressed ATXN3 in C33A, HeLa, and SiHa cells, with HeLa exhibiting the highest induction—approximately fivefold greater than the other lines." (PMID 41507147, 2026). "In conclusion, our study establishes ATXN3 as a clinically relevant biomarker and context-dependent regulator in cervical cancer pathogenesis." (PMID 41507147, 2026). "As JAK3 is a well-established upstream kinase of STAT5 and has been reported to play a critical role in cervical cancer progression, we modeled ATXN3’s interaction with phosphorylated JAK3 (p-JAK3, Y980)." (PMID 41507147, 2026). "Following ATXN3 siRNA transfection, mRNA and protein levels were successfully reduced in all three cervical cancer cell lines, with the most pronounced decrease observed in HeLa cells." (PMID 41507147, 2026). "In cervical cancer and colorectal cancer, downregulation of ATXN3 suppresses tumour cell apoptosis, thereby exerting tumour‐promoting effects." (PMID 40995818, 2025). "The regulatory network controlling ATXN3 expression in cervical cancer remains poorly understood." (PMID 41507147, 2026).
non-small cell lung carcinoma (2 papers, 2020 to 2022). A group of at least three distinct histological types of lung cancer, including non-small cell squamous cell carcinoma, adenocarcinoma, and large cell carcinoma. "In Ataxin-3-depleted non-small-cell lung cancer, mRNAs of PTEN and PTENP1 decay rapidly with transcriptional inhibition as Ataxin-3 acts primarily by repressing their transcription." (PMID 32982735, 2020).